GATA1 (GATA binding protein 1)
Diseases named in the same sentence as GATA1 in open-access papers (continued):
Sharing a sentence is not in itself a finding about the gene and the disease.
Down syndrome (continued). "In the Oxford Imperial Down Syndrome Cohort (OIDSC) Study, we addressed this question by prospectively classifying cases with blasts of >10 % and a GATA1 mutation in the first 14 days of life as TAM." (PMID 27510823, 2016). "Application of highly sensitive next-generation sequencing (NGS)-based methodology has recently shown that GATA1 mutations are present in all cases of TAM or ML-DS and that they are present in 25–30 % of all neonates with Down syndrome [11••]." (PMID 27510823, 2016). "One is a structural mutation in the GATA1 gene, resulting in the production of a short form of GATA1 that lacks the N-terminal transactivation domain and is found in Down syndrome-related acute megakaryocytic leukemia." (PMID 28119852, 2016). "Acquired mutations in GATA1 are tightly associated with acute megakaryoblastic leukemia (AMKL) and transient abnormal myelopoiesis (TAM) in children with Down syndrome (DS)." (PMID 26445707, 2015). "Somatic GATA1 mutations that lead to the exclusive production of GATA1s appear to be necessary and sufficient for the development of a preleukemic condition called transient myeloproliferative disorder (TMD) in Down syndrome newborns." (PMID 38409186, 2024). "Germ-line and somatic GATA1 gene mutations that produce a short form of GATA that lacks the N-terminal transactivation domain are causal in Diamond–Blackfan anemia and preleukemic disease in Down syndrome patients, respectively." (PMID 28119852, 2016). "The presence of multiple GATA1 mutant clones in up to 25 % of neonates with Down syndrome is consistent with this [9, 11••]; however, the reason for their high frequency in Down syndrome remains unknown (these mutations are not found in normal, disomic cord blood) [9, 11••]." (PMID 27510823, 2016). "Although TAM is characterised by increased peripheral blood blasts, it is now known that blast cells are seen on the blood film of almost all neonates (∼98 %) with Down syndrome and may account for 15–20 % of the circulating leucocytes in neonates shown to have no GATA1 mutations [11••]." (PMID 27510823, 2016). "Unlike other GATA members, GATA-1 has not been associated with any solid tumors, but mutations in GATA-1 are associated with essentially all cases of acute megakaryoblastic leukemia in children with Down syndrome." (PMID 21689417, 2011).
Thrombocytopenia (35 papers, 2010 to 2025). A reduction in the number of circulating thrombocytes. "The downregulation of GATA1 expression results in impaired megakaryopoiesis, causing thrombocytopenia." (PMID 40937321, 2025). "To identify biomarkers associated with BET inhibition induced thrombocytopenia, we initially conducted transcriptional profiling of GATA1, which showed significant (p < 0.05) decreased expression in blood from patients treated with 4.5 mg BMS-986158." (PMID 40937321, 2025). "When germline mutation occurs in GATA1, it causes a variety of X-linked recessive forms of hereditary thrombocytopaenia and dyserythropoietic anaemia." (PMID 38961467, 2024). "In this study, we examined three pedigrees with thrombocytopenia and platelet dysfunction associated with genetic variants in the GATA1 gene." (PMID 36291092, 2022). "Till to date, a total of 66 SNPs within GATA1 have been reported to be associated with different diseases including thrombocytopenia and Diamond-Blackfan anemia." (PMID 35771876, 2022). "A very rare GATA1 variant (p.*414Arg) enlarging GATA-1 is associated with the rare X-linked blood group Lu(a-b-) phenotype and mild macrothrombocytic thrombocytopenia." (PMID 36291092, 2022). "On the contrary, we present two brothers with the p.D218N variant in the GATA1 N-ZF domain who suffered from bleeding symptoms and thrombocytopenia." (PMID 36291092, 2022). "The current study elucidated an association between gene variants and thrombocytopenia through the investigation of the exonic polymorphic landscape of hematopoietic transcription factor—GATA1 gene in dengue patients." (PMID 35771876, 2022). "The exonic polymorphism landscape of hematopoietic transcription factor—GATA1 in dengue patients was investigated in our study to see if there is an association between genetic variations and thrombocytopenia." (PMID 35771876, 2022). "It is known that the GATA1 gene located in Xp11.23 is involved in the differentiation of blood cells, and mutations of this gene are linked to thrombocytopenia and dyserythropoietic anemia." (PMID 33920939, 2021). "There have been reports of x—linked CEP patients carrying a GATA1 mutation with misleading hematological phenotypes that include dyserythropoietic anemia, thrombocytopenia and hereditary persistence of fetal hemoglobin." (PMID 28899405, 2017). "In summary, Gata1 loss in the megakaryocytic lineage leads to -chronic- thrombocytopenia and dysfunctional platelets." (PMID 27152938, 2016). "Mutations in GATA1 have been reported to result in thrombocytopenia." (PMID 40937321, 2025). "Acquired and inherited mutations in GATA1 contribute to Diamond–Blackfan anemia, acute megakaryoblastic leukemia, transient myeloproliferative disorder and a group of related congenital dyserythropoietic anemias with thrombocytopenia." (PMID 36765901, 2023). "Notably, different positions of the GATA1 pathogenic variants result in a remarkably high variety of phenotypes encompassing ineffective erythropoiesis, neutropenia, thrombocytopenia, and thrombocytopathy." (PMID 36291092, 2022). "These are the first reported GATA1 variants that are located in the C-terminal zinc finger region and are associated with bleeding symptoms, platelet dysfunction, and only borderline/mild thrombocytopenia." (PMID 36291092, 2022). "This study was aimed to investigate potential variations within entire exonic regions of GATA1 gene, one of the master transcription factor for platelet production, in dengue patients with thrombocytopenia and thus, establishes a relationship between gene variants and disease severity." (PMID 35771876, 2022). "In summary, we have identified new variants within the GATA1 gene which were found to be clinically relevant to the outcome of dengue patients and thus, have the potential as candidate biomarkers for the determination of severity and prognosis of thrombocytopenia caused by dengue virus." (PMID 35771876, 2022).
Thrombocytopenia (continued). "However, whether these events occur only in the context of Gata1 loss or are merely due to the severe prolonged thrombocytopenia (or both), needs to be further investigated." (PMID 27152938, 2016). "However, we cannot conclude whether this aberrant megakaryocytic stage is dependent on Gata1 loss, or a consequence of the thrombocytopenia or stress megakaryopoiesis itself." (PMID 27152938, 2016). "Interestingly, point mutations in humans that disrupt GATA-1/FOG-1 interaction are associated with familial dyserythropoietic anemia and thrombocytopenia, and a point mutation in GATA-1 that inhibits FOG-1 binding cannot rescue erythroid differentiation in a GATA-1 deficient cell line." (PMID 22235346, 2012). "Our study demonstrates that BET inhibition induces thrombocytopenia in vivo by altering GATA1 gene expression and its downstream genes, NFE2 and PF4, which regulate megakaryopoiesis and thrombopoiesis." (PMID 40937321, 2025). "The association of thrombocytopenia and red cell abnormalities is characteristic of certain IT subtypes, such as that associated with GATA-1 disease-causing variants (GATA1-RT)." (PMID 40563486, 2025). "For example, GATA1 knock-out mice display thrombocytopenia accompanied by an increase in the number of MKs that are characterized by decreased polyploidization and a defect in cytoplasmic maturation." (PMID 38617546, 2024). "Several lines of reports indicate that defects in GATA1 activity lead to thrombocytopenia, structural abnormalities in megakaryocytes, and impairment of platelet activation." (PMID 37534186, 2023). "These genes include HEXA (Tay-Sachs disease), CDKN1B (Neoplasia), GATA1 (Thrombocytopenia, Thalassemia), and SH2D1A (Lymphoproliferative syndrome)." (PMID 38033082, 2023). "Pathogenic germline variants in genes encoding the prominent transcription factors RUNX1, GATA1, FLI1, GFI1b, and ETV6 are known to cause thrombocytopenias, associated with large and normal platelet size, respectively." (PMID 36231035, 2022). "Importantly, the inherited GATA1 V205M mutation is associated with familial dyserythropoietic anemia and thrombocytopenia in patients, once again highlighting the importance of a functional FOG-1/GATA1 interaction in hematopoiesis." (PMID 40048486, 2025). "Hence the cleavage of EDRF1 observed in the present study led to decreased levels of GATA1 and subsequently to fewer spectrins and finally to the reduced number of platelets, i.e., thrombocytopenia." (PMID 37534186, 2023). "We have identified new GATA1 gene variations that were proven to be clinically related to the outcome of dengue patients and hence holds the potential to be candidate biomarkers for determining the severity and prognosis of dengue thrombocytopenia." (PMID 35771876, 2022). "As a result, synonymous variation to less frequent codon could lead to altered expression of GATA1 protein which eventually may affect thrombopoiesis followed by thrombocytopenia." (PMID 35771876, 2022). "However, there are only very few studies reporting a reduced number of both platelet α-granules and δ-granules in GATA1-related thrombocytopenia." (PMID 36231035, 2022). "cAMP enhances megakaryopoiesis through PKA-mediated activation of RUNX1 and GATA1, while its depletion in BDS likely exacerbates thrombocytopenia." (PMID 40332770, 2025). "Furthermore, thrombocytopenia related to telomere length, GATA1 and MYH9-variants was ruled out." (PMID 34858435, 2021). "GATA1 affects NFE2 and PF4, influencing thrombopoiesis and leading to thrombocytopenia." (PMID 40937321, 2025). "We think that these latter events are a consequence of the -chronic- thrombocytopenia, rather than Gata1 gene recombination in the megakaryocytic lineage itself." (PMID 27152938, 2016). "In fact, thrombocytopenia driven by recombinant IFN α has been related to the selective inhibition of cytoplasmic maturation accompanied by downregulation of the expression of the transcription factors NF-E2, GATA-1 and MafG/HPRT." (PMID 20419155, 2010).
Thrombocytopenia (continued). "The shift could potentially be explained by the severe and chronic thrombocytopenia suffered by Gata1cKOMK mice; still we could not discard Gata1-dependent or -independent alterations in relevant factors such as Pf4 or TPO to be causative of the misbalance observed at the progenitor level." (PMID 27152938, 2016). "Without adequate GATA1 activity, PF4 expression is reduced, leading to impaired megakaryocyte development and subsequent thrombocytopenia." (PMID 40937321, 2025).
acute megakaryoblastic leukemia (31 papers, 2011 to 2025). Acute megakaryoblastic leukemia (AMKL) is a form of acute myeloid leukemia (AML) that occurs predominantly in childhood and particularly in children with Down syndrome (DS-AMKL). "GATA1 is also implicated in the development of acute megakaryoblastic leukemia (AMKL)." (PMID 23311859, 2013). "In DS patients, there is a notable prevalence of acute myeloid leukemia (AML), particularly acute megakaryoblastic leukemia (AMKL), which is often associated with mutations in GATA1, the gene encoding the GATA1 transcription factor." (PMID 38962468, 2024). "Leukemogenesis of acute megakaryoblastic leukemia (AMKL) in DS patients is associated with the presence of somatic mutations involving GATA 1 gene (or also called as GATA-binding factor 1)." (PMID 26062604, 2015). "Co-expression of ERG and the short isoform of Gata1 (Gata1s, universally expressed in Down syndrome’s myeloid malignancies), led to transient myeloproliferative disorder and acute megakaryocytic leukemia (AMKL) in mice." (PMID 37735473, 2023). "The observations in human patients confirmed the critical role for GATA1 in erythroid and megakaryocytes development, and GATA1 mutations may be closely related to two neoplastic diseases: transient myeloproliferative disorder and acute megakaryoblastic leukemia." (PMID 35488350, 2022). "Overexpression of GATA1 promoted chemotherapy resistance in acute megakaryocytic leukemia and in pancreatic cancer." (PMID 34832908, 2021). "Acquired and inherited GATA1 mutations contribute to hematological disorders such as Down syndrome acute megakaryoblastic leukemia (AMKL), Diamond-Blackfan anemia, transient myeloproliferative disorder and congenital dyserythropoietic anemias with thrombocytopenia." (PMID 31628330, 2019). "Consistent with this idea, genetic disorders that impair GATA1 function often result in both the dysregulation of erythropoiesis as well as an increased incidence of transient myeloproliferative disorder and/or acute megakaryoblastic leukemia in a subset of patients." (PMID 34016988, 2021). "Furthermore, we found that the histone deacetylase (HDAC) inhibitor, valproic acid (VPA), can decrease GATA1 expression and synergize with ara-C in exerting antileukemic activities toward megakaryocytic leukemia cells." (PMID 23874683, 2013). "This short GATA1 isoform increases the possibility to develop acute megakaryoblastic leukemia (AMKL)." (PMID 27152938, 2016). "In the absence of Gata1 erythroid progenitors undergo apoptosis whereas megakaryocytes fail to undergo terminal differentiation and expand dramatically Megakaryocyte proliferation promotes development of acute megakaryoblastic leukemia (AMKL) frequently associated with Down syndrome (DS)." (PMID 34736527, 2021).
breast carcinoma (24 papers, 2011 to 2025). "GATA1 has been ascertained to be associated with cell phenotypes and development of solid tumors such as colorectal cancer, breast cancer and ovarian cancer." (PMID 39695810, 2024). "However, the underlying mechanisms for GATA1 deSUMOylation in breast cancer invasion and metastasis are unknown." (PMID 35342335, 2022). "Research in human breast cancer cells also identified GATA1 as a negative regulatory factor on the target gene, which is consistent with what we observed in our study." (PMID 40075948, 2025). "In breast cancer, GATA1 was found to be overexpressed, and it was demonstrated to promote survivin expression." (PMID 39684309, 2024). "As for angiogenesis, GATA1 has been reported to interact with the histone methyltransferase SET7 to trigger VEGF-induced angiogenesis in breast cancer." (PMID 35491849, 2022). "In clinical breast cancer samples, both GATA1 and SET7/9 are overexpressed and their expression levels were significantly correlated with tumor size, grade, and VEGF expression." (PMID 35069908, 2022). "For example, GATA1 is highly expressed in breast cancer 24 and involved in breast cancer epithelial-mesenchymal transition (EMT) process, promoting its invasion and metastasis 25-27." (PMID 35342335, 2022). "The expression of GATA-1 has been shown to be upregulated in breast cancer and repress the E-cadherin transcription by binding to the E-cadherin promoter and recruiting HDAC3/4." (PMID 31783675, 2019). "In breast cancer and colorectal cancer, GATA1 was reported to be overexpressed compared with matched adjacent normal tissues." (PMID 31093285, 2019). "GATA1 is also a promoter binder factor of peroxiredoxin 5 in human breast cancer cells through inhibiting apoptosis." (PMID 30872657, 2019). "This implies that GATA1-regulated Prdx5 transcription can be targeted to treat breast cancer, but it requires further analysis involving the overexpression of GATA1 and its effects on tumor production and metastasis." (PMID 31500275, 2019). "GATA1 transcription factor binds to the promoter region of Prdx5 in breast cancer cells and downregulates the transcription of Prdx5." (PMID 31500275, 2019). "SNPs in cis-acting elements such as GATA-1 transcription factor binding sites enhance the promoter activity of the survivin gene in breast cancer patients." (PMID 29299175, 2017). "Taken together, these findings implicated the significance of GATA1 and SET7 in breast cancer prognosis." (PMID 26848522, 2016). "GATA1 enhanced breast cancer cell (MCF7, ZR75-1 and MDA-MB-231)-secreted VEGF via SET7, which promoted vascular endothelial cell (HUVEC) proliferation, migration and tube formation." (PMID 26848522, 2016). "The conditioned medium from GATA1-overexpreesing breast cancer cells increased HUVEC proliferation, migration and tube formation as well as angiogenesis in the CAM model." (PMID 26848522, 2016). "GATA1 inhibits the expression of the epithelial-mesenchymal transition marker E-cadherin and promotes breast cancer cell metastasis in vivo." (PMID 26848522, 2016). "CAM treated with the conditioned medium from GATA1 knockdown breast cancer cells had reduced number of new blood vessels and reexpression of GATA1 in GATA1 knockdown cells abolished this effect." (PMID 26848522, 2016). "Inhibition of cancer cell-secreted VEGF by a VEGF neutralizing antibody abrogated the ability of the conditioned medium from GATA1-overexpressing breast cancer cells to increase HUVEC tube formation." (PMID 26848522, 2016). "Since GATA1 promotes VEGF secretion in breast cancer cells, we determined the effect of the conditioned medium derived from GATA1 overexpression or knockdown stable breast cancer cell lines on HUVEC proliferation and migration." (PMID 26848522, 2016). "To investigate how GATA1 promotes VEGF transcription in breast cancer cells, we first determined the binding site of GATA1 on the VEGF promoter." (PMID 26848522, 2016).